SCML2 (Scm polycomb group protein like 2)
Description:
Putative Polycomb group (PcG) protein. PcG proteins act by forming multiprotein complexes, which are required to maintain the transcriptionally repressive state of homeotic genes throughout development (By similarity).
Tractability: Small molecule: a structure with a bound ligand is known. PROTAC: UniProt records ubiquitination sites on it; ubiquitination databases record sites on it.
Gene: Protein-coding gene on chromosome X (18,239,307 to 18,355,149, reverse strand). Ensembl gene ENSG00000102098.
Subcellular location: Nucleus
Subcellular location (Human Protein Atlas): Cytosol; Nucleoli
Gene Ontology:
Molecular function: protein binding; chromatin binding; histone binding
Biological process: anatomical structure morphogenesis; negative regulation of DNA-templated transcription; regulation of DNA-templated transcription
Cellular component: nucleus; PcG protein complex
Homologues: Orthologues: chimpanzee SCML2 (99% identical), macaque SCML2 (98% identical), dog SCML2 (81% identical), pig SCML2 (80% identical), rabbit SCML2 (55% identical), tropical clawed frog scml2 (54% identical), mouse Scml2 (52% identical), rat Scml2 (52% identical), zebrafish scml2 (49% identical), Drosophila melanogaster l(3)mbt (15% identical), Drosophila melanogaster Sfmbt (13% identical), Caenorhabditis elegans lin-61 (12% identical), and 1 more. Paralogues in human: SCMH1 (45% identical), SFMBT2 (26% identical), SFMBT1 (25% identical), L3MBTL4 (20% identical), SCML4 (20% identical), L3MBTL3 (19% identical), L3MBTL1 (19% identical), L3MBTL2 (15% identical), MBTD1 (14% identical), PHC3 (14% identical), PHC2 (14% identical), PHC1 (13% identical), and 6 more.
Diseases named in the same sentence as SCML2 in open-access papers:
SCML2 is named in the same sentence as 8 diseases in open-access papers, as found by Europe PMC text mining. Sharing a sentence is not in itself a finding about the gene and the disease. The quoted sentences say what the papers report.
medulloblastoma (3 papers, 2013 to 2014). A malignant, invasive embryonal neoplasm arising from the cerebellum. "The SCML2 gene is deleted in a subset of medulloblastomas, suggesting a role in tumor suppression." (PMID 24358021, 2013). "It will be important to determine whether the role of LIN-61 in DSB repair is conserved in human MBT proteins and whether MBT mutated tumours, such as medulloblastomas with mutations in L3MBTL2, L3MBTL3 or SCML2, are HR deficient as they too may prove responsive to treatment with PARP inhibitors." (PMID 23505385, 2013). "Indeed, the absence of scm in Drosophila induces an increase in proliferation similar to that associated with defects in PRC1 components, and human SCML2 and other MBT-containing genes are focally deleted in medulloblastomas and breast cancer." (PMID 24358021, 2013).
acute myeloid leukemia (1 paper, 2013). Acute myeloid leukemia (AML) is a group of neoplasms arising from precursor cells committed to the myeloid cell-line differentiation. "Deregulation of the expression of SCML2 has also been observed in acute myeloid leukemia and in several T-cell malignancies." (PMID 24358021, 2013).
Infertility (1 paper, 2023). "Since we were able to rescue the infertility of Scml2-KO male with ICSI using testicular sperm, we sought to determine how the sperm epigenome is regulated in testicular sperm prior to its maturation to epididymal sperm." (PMID 37283086, 2023). "We rescued the infertility of Scml2-KO males and demonstrated that the Scml2-KO mouse line serves as a novel model of epigenetic inheritance, particularly that of paternal epigenetic states." (PMID 37283086, 2023). "To test the functions of SCML2 in paternal epigenetic inheritance, we sought to recover the infertility of Scml2-KO mice by ART." (PMID 37283086, 2023). "Notably, ICSI using testicular sperm rescued infertility of Scml2-KO males, and these pups underwent full-term development with apparently normal placentas at a comparable frequency with that of controls." (PMID 37283086, 2023). "By applying modified methods of assisted reproductive technology using testicular sperm, we rescued infertility of mice missing Polycomb protein SCML2, which regulates germline gene expression by establishing H3K27me3 on bivalent promoters with other active marks H3K4me2/3." (PMID 37283086, 2023).
pancreatic cancer (1 paper, 2017). "We also identified novel pancreatic cancer genes, such as SCML2, COL17A1, AMIGO2, PTPRR, suggesting our method might be able to predict novel PDAC-related genes." (PMID 28611293, 2017).
tumor (5 papers, 2013 to 2025). "In the TCGA-UCEC dataset, APOBEC3G, CUL4B, SCML2, TSPYL5, and ZBTB16 were significantly downregulated in tumor samples, whereas FOXP3, HJURP, HMGB3, and RAC3 were significantly upregulated in tumor samples, which was generally consistent with the result observed in GSE17025." (PMID 36936912, 2023). "SCML2 is not a direct target for miR302-367 cluster, but it is known to repress transcription and is considered as tumor suppressor." (PMID 26094604, 2015).
cancer (2 papers, 2013 to 2015). A tumor composed of atypical neoplastic, often pleomorphic cells that invade other tissues. "Therefore, Scml2 should be considered as a cancer/testis gene and might be implicated in tumorigenesis." (PMID 25634095, 2015). "Consistent with its interaction with PRC1 and binding to chromatin, SCML2 has profound impact on the cellular activity when ectopically expressed in transformed or cancer cells." (PMID 25634095, 2015). "Recent studies have demonstrated that human SCML2 is expressed in a variety of somatic cells—immortal and cancer cell lines." (PMID 25634095, 2015). "Although a possible role for the SCML2 gene in cancer has already been suggested, the lack of functional information on the proteins that it encodes has hampered the elucidation of its mechanism of action." (PMID 24358021, 2013).
SCML2 also shares sentences with these, for which no sentence is quoted: breast carcinoma (1 paper); lymph node metastasis (1).